ABCB4 (ATP binding cassette subfamily B member 4)
Diseases named in the same sentence as ABCB4 in open-access papers (continued):
Sharing a sentence is not in itself a finding about the gene and the disease.
glioblastoma (2 papers, 2024). The most malignant astrocytic tumor (WHO grade IV). "Subsequently, the co-localisation of ABCB4 and CD133, a recognised marker of GSCs, was examined in glioblastoma tissues using confocal microscopy." (PMID 38710703, 2024). "Recently, it has been reported that chemoresistance is due, at least in part, to the high expression, in glioblastoma stem cells (GSCs), of members, such as ABCB4, of the ATP-binding cassette (ABC) transporters; moreover, ABCB4 can be transferred to the neighboring cells via EVs." (PMID 39194524, 2024).
squamous cell carcinoma (2 papers, 2014 to 2015). A carcinoma arising from squamous epithelial cells. "ABCB4 staining was slightly higher in squamous cell carcinoma (18/30 or 60%) than in adenocarcinoma (8/14 or 57%)." (PMID 25367630, 2014). "ABCB4 staining was dominantly cytoplasmic, but about 24% of the cases (mainly squamous cell cancer and SCLC) also showed nuclear staining." (PMID 25367630, 2014).
arteriosclerosis (1 paper, 2007). A vascular disorder characterized by thickening and hardening of the walls of the arteries. "In parallel to arteriosclerosis, enhanced cholangiocellular VCAM-1 expression was recently demonstrated in multidrug resistance gene (Mdr2/Abcb4) knockout mice (Mdr2-/-), a well characterized mouse model that closely mirrors the macroscopic and microscopic pathology of PSC." (PMID 17254334, 2007).
atherosclerosis (1 paper, 2017). A disease characterized by the build-up of fatty material and calcium deposition in the arterial wall resulting in partial or complete occlusion of the arterial lumen. "Animal studies using depletion and subsequent transplantation of ABCB4−/− bone marrow cells into an atherosclerosis mouse model had opposing effects on disease parameters, yet in the end, aggravated atherosclerosis pathology." (PMID 28383515, 2017).
Becker muscular dystrophy (1 paper, 2024). Becker muscular dystrophy (BMD) is a neuromuscular disease characterized by progressive muscle wasting and weakness due to degeneration of skeletal, smooth and cardiac muscle. "At age 13, he was diagnosed Becker muscular dystrophy carrying with the causative mutation in gene DMD (chrX:32,841,413–32,862,977, Hemizygous mutation), and gene testing showed the comorbid mutations of ABCB4(chr7:87041219, heterozygous mutation) and DSC2(chr18:28659938, heterozygous mutation)." (PMID 39044225, 2024).
cervix cancer (1 paper, 2014). "Hypermethylation of ABCB4 was found in several epithelial cancer entities including lung, breast, head and neck (HN), skin and cervix cancer." (PMID 25367630, 2014).
chronic hepatitis C (1 paper, 2019). "One patient with chronic hepatitis C showed inhomogeneous, weak expression of ABCB11 and ABCB4, and one FNH patient, accumulation of ABCB4 in some areas, but a homogeneous expression of ABCB11 at the bile canalicular membrane of adjacent hepatocytes (Supplementary and Supplementary )." (PMID 31886153, 2019).
cutaneous leishmaniasis (1 paper, 2022). Leishmaniasis affecting the skin. "In this study, we evaluated ABCI4, ABCG2, ABCC7, ABCB4, and ABCC3 genes expression in Leishmania isolated from patients with non-healing cutaneous leishmaniasis and treatment response isolates." (PMID 35710996, 2022).
epilepsy (1 paper, 2011). A brain disorder characterized by episodes of abnormally increased neuronal discharge resulting in transient episodes of sensory or motor neurological dysfunction, or psychic dysfunction. "Five genes, ABCB1, ABCB4, CHRNA7, GABRA1, and GABRG2, are located within reported CNV regions and have been studied previously for their association with epilepsy as collected by HuGE." (PMID 21390307, 2011).
gallbladder disease (1 paper, 2015). "Of note, a Thr175Val variation at the same position has been previously related to gallbladder disease in a sporadic case, while ABCB4 mutations are usually associated with familial forms of the disease." (PMID 25888430, 2015).
Glycogen storage disease type-III (1 paper, 2025). "Variants in AGL (Glycogen storage disease type-III; GSD3), ABCB4 (Progressive familial intrahepatic cholestasis type-III; PFIC3) and ABCB11 (PFIC2) genes were the most common affecting 19, 14 and 13 children, respectively." (PMID 41165782, 2025).
head and neck cancer (1 paper, 2014). A primary or metastatic malignant neoplasm affecting the head and neck. "We investigated the epigenetic regulation of ABCB4 in 26 human lung, breast, skin, liver, head and neck cancer cells lines and in primary cancers by methylation and expression analysis." (PMID 25367630, 2014).
hepatobiliary tumors (1 paper, 2023). "This feature of our assay is put into context by recent studies that point to the importance of ABCB4 in non-hepatobiliary tumors." (PMID 36901890, 2023).
Hypercalcemia (1 paper, 2014). An abnormally increased calcium concentration in the blood. "Serum calcium levels were slightly higher in Abcb4−/− mice as compared to wild-type controls in all dietary groups, and no hypercalcemia was induced." (PMID 25191532, 2014).
intestinal tumor (1 paper, 2016). "In line with the reduced epithelial proliferation observed in the intestine of Abcb4−/− mice, ApcMin/+/Abcb4−/− mice displayed protection against intestinal tumor formation, when compared to ApcMin/+/Abcb4+/+." (PMID 27995969, 2016). "Also in ApcMin/+/Abcb4−/−, the introduction of dietary PC was able to restore the intestinal tumor number very close to the one of ApcMin/+/Abcb4+/+." (PMID 27995969, 2016). "Thus, both the genetically induced and carcinogen-induced models of intestinal tumors show that Abcb4−/− mice are protected against intestinal carcinogenesis, and that a diet supplemented with PC completely overcomes this protection." (PMID 27995969, 2016). "Feeding Abcb4−/− mice a diet supplemented with phospholipids completely overcomes the intestinal tumor protective phenotype, thus corroborating the hypothesis that the absence of biliary phospholipids and not lack of Abcb4 gene per se is responsible for the protection." (PMID 27995969, 2016). "Remarkably, absence of biliary phospholipids in Abcb4−/− mice leads to protection against intestinal tumorigenesis in both the genetically induced and carcinogen-induced models of intestinal tumors." (PMID 27995969, 2016).
mesothelioma (1 paper, 2014). A usually malignant and aggressive neoplasm of the mesothelium which is often associated with exposure to asbestos. "The highest expression of ABCB4 was observed in SCLC, while no staining was observed in mesotheliomas." (PMID 25367630, 2014).
nodular goiter (1 paper, 2011). Goiter characterized by discrete tissue mass(es) that may or may not produce thyroid hormones. "ABCB4 belongs to the multidrug resistance subfamily, encoding a full transporter and member of the p-glycoprotein family of membrane proteins with phosphatidylcholine as its substrate, which was more frequently methylated in normal thyroid tissue compared with nodular goiter in the present study." (PMID 21988780, 2011). "Among of them, there was a significantly distinct methylation profiling of ABCB4, CYP1B1 and CYP24A1 and SLC1A2 between nodular goiter and normal thyroid tissues (P < 0.05)." (PMID 21988780, 2011).
prostate tumor (1 paper, 2021). "Using one probe, XLB, here we identified ATP-binding cassette (ABC) transporters ABCA3, ABCB4, and ABCB10 as unfractionated microsomal GlcCer-binding proteins in DU-145 prostate tumor cells." (PMID 34597626, 2021).
tumor (50 papers, 1993 to 2025). "Furthermore, caused by the hypermethylation of CpG promoter, ABCB4 is epigenetically silenced to initiate the tumor growth." (PMID 29371412, 2018). "Similarly, a diet enriched in phosphatidylcholine restored tumor susceptibility in Abcb4−/− mice only in presence of a functional intestinal Lrh1 transcriptional pathway." (PMID 27995969, 2016). "Recently, accumulating evidence indicates that ABCB4 has a close relationship with tumor progression." (PMID 36866272, 2023). "To investigate potential clinical significance of ABCB4, we analyzed the expression of ABCB4 in normal and tumor tissues from the clinical patients." (PMID 29371412, 2018). "At the molecular level, the transcriptional activity of the nuclear receptor Liver Receptor Homolog-1 (Lrh1) is reduced in Abcb4−/− mice and its re-activation re-establishes a tumor burden comparable to control mice." (PMID 27995969, 2016). "To functionally test ABCB4 and its ability to suppress tumor formation, we performed colony formation and proliferation assays." (PMID 25367630, 2014). "In normal human bronchial epithelial cells, mammary epithelial cells and fibroblast ABCB4 was unmethylated, but in primary tumor tissues aberrant promoter methylation of ABCB4 was revealed." (PMID 25367630, 2014). "Bioluminescence imaging analysis shows ABCB4 knockdown significantly inhibited tumour growth." (PMID 38710703, 2024). "In summary, we identified the HIF-1α-mediated induction of ABCB4 as a mechanism for effluxing [18F]-D4-FCHP species within hypoxic tumours, with implications for the use of [18F]-D4-FCH and other radiolabelled choline species for monitoring the anticancer therapy response." (PMID 34452207, 2021). "As expected, ABCB4 was significantly decreased in the tumor tissues of TCGA(COADREAD) Cohort." (PMID 29371412, 2018). "Compared with the p-tumor tissues, ABCB4 was significantly lower in the recurrent tumor tissues." (PMID 29371412, 2018). "To verify ABCB4 as a tumor suppressor, we ectopically expressed the ABCB4 in HCT8R cells." (PMID 29371412, 2018). "Increased tumor size went along with pronounced angiogenesis in Abcb4−/−/HBsAg+/− mice." (PMID 28881751, 2017). "Interestingly, heterozygosis for Abcb4 gene in ApcMin/+/Abcb4+/− mice resulted in a tumor phenotype intermediate between ApcMin/+/Abcb4+/+ and ApcMin/+/Abcb4−/− mice." (PMID 27995969, 2016). "Besides, ABCB4 was down-regulated in the primary tumor tissues and recurrent tissues." (PMID 29371412, 2018). "This occurs through the transfer of ABCB4 protein to differentiated glioma cells via exosomes, effectively fostering a microenvironment resistant to TMZ therapy within the tumor." (PMID 40143161, 2025). "The results showed that relative to normal samples, proteins (ABCB4, FAM53B, and INTU) were significantly dysregulated in tumor tissues." (PMID 34717651, 2021). "ABCB4 (also known as MDR3) is closely related to ABCB1 (78% identity), and like ABCB1, can act as a drug efflux pump contributing to tumor drug resistance." (PMID 34597626, 2021). "We report herein that only in Abcb4−/− mice INT-767 is able to reduce bile toxicity by decreasing total BA output in a FXR-dependent manner, thus preventing BA-induced tumor promoting effects." (PMID 28894223, 2017). "Notably, GSCs not only exhibit intrinsic resistance to TMZ due to the high expression of the ABCB4 efflux pump, particularly evident in CD133-positive GSCs, but also contribute to the development of a broader tumor resistance." (PMID 40143161, 2025). "Bioluminescence imaging analysis revealed that knockdown of the ABCB4 gene did not exert a significant impact on tumour growth." (PMID 38710703, 2024). "There were no significant changes in expression between the tumor and control tissues in the ABCB4, ABCA13, ABCC2, ABCC3, and ABCG2 genes." (PMID 36674773, 2023).
tumor (continued). "Notably, several well-characterized cancer-related genes (e.g., ZKSCAN1, ABCB4 and CYP2C8) were found to generate circRNAs with significant changes in tumor samples." (PMID 31900416, 2020). "To better clarify the role of Lrh1 in mediating the effects of phospholipids in tumor promotion, we sought to investigate the absence of intestinal Lrh1 (iLrh1−/−) in Abcb4−/− mice." (PMID 27995969, 2016). "Interestingly, dietary phospholipids were not able to increase intestinal tumor formation in Abcb4−/− mice in absence of intestinal Lrh1." (PMID 27995969, 2016).
cancer (34 papers, 2010 to 2025). A tumor composed of atypical neoplastic, often pleomorphic cells that invade other tissues. "A previous study provided evidence that loss of ABCB4 enhances the cell proliferation in many cancers." (PMID 29371412, 2018). "It will be interesting to evaluate if aberrant ABCB4 methylation may represent a novel biomarker for prognostic or diagnostic purposes in human cancer." (PMID 25367630, 2014). "Many of these genes, including ABCB4 (MDR3), ADAM22, and DBF4, have been implicated in cancer development and MDR, and are considered possible therapeutic targets." (PMID 39199583, 2024). "Further, microRNAs inhibit cancer cell proliferation and metastasis, and melatonin-induced miR-392a and miR-34b increase cancer cell apoptosis by inhibiting ABCB1/ABCB4 activity." (PMID 33546749, 2021). "In summary, germline variants in many of the VIPs of CYP and ABC superfamilies as well as in other genes (ABCB4, ABCC1-C4, CYP1A1, and CYP1B1) are associated with drug response in cancer." (PMID 32872162, 2020). "Recently reviewed information suggested that an ABCB1 locus including another transporter ABCB4 is frequently amplified in cancer and mainly in tumors or in vitro models with induced drug resistance." (PMID 32872162, 2020). "Impairing activity and expression of P-gp and ABCB4 by curcumin results in enhanced internalization of DOX in cancer cells and providing chemosensitivity." (PMID 33187385, 2020). "Inspite of some controversies, ABCB4 is worthy of consideration as a target for illustrating the resistance in human cancers." (PMID 29371412, 2018). "Knockdown of ABCB4 suppresses the caspase-dependent apoptosis pathway, which is canonical in regulating the resistance in cancer." (PMID 29371412, 2018). "Silencing of ABCB4 was reversed by 5-aza-2'-deoxycytidine and zebularine treatments leading to its reexpression in cancer cells." (PMID 25367630, 2014). "In our study, we have identified the ATP-binding cassette sub-family B member 4 (ABCB4) as novel epigenetically inactivated target gene in human cancer." (PMID 25367630, 2014). "Our results show that ABCB4 significantly suppresses colony growth in H322 and A427 cancer cells, in which ABCB4 is downregulated and inactivated by aberrant promoter methylation." (PMID 25367630, 2014). "Hypermethylation of the ABCB4 CpG island promoter occurred in 16 out of 26 (62%) human cancer cell lines." (PMID 25367630, 2014). "In cancer, we observed an epigenetic silencing of ABCB4, which was reversed by Aza or Zebu treatment." (PMID 25367630, 2014). "Sequencing of exosomes secreted by cancer cells has revealed the presence of ABCB4, suggesting that ABCB4 may transmit drug resistance between cells through exosomes." (PMID 38710703, 2024). "On the NR0B2 cell trajectory of Abcb4−/− cholangiocytes, some molecules implicated in carcinogenesis were evidenced: GSTA3, ID2, and TMEM45A, which is a transmembrane molecule considered to be oncogenic in several cancers." (PMID 39130146, 2023). "Increasing evidences have shown ABCB4 plays a part in the cancer resistance and growth." (PMID 29371412, 2018). "These previous researches support the hypothesis that ABCB4 may function in cancers via inactivation." (PMID 29371412, 2018). "Thus, 26 cancer cell lines were analyzed, of which 16 (62%) were methylated for ABCB4 and its hypermethylation was found in different human cancer entities including lung, breast, skin and HN cancers." (PMID 25367630, 2014). "Thus, our data suggest that epigenetic silencing of Abcb4 occurred also in pathogenesis of murine cancer." (PMID 25367630, 2014). "Demethylation of ABCB4 is accompanied by its reexpression in cancer cell lines." (PMID 25367630, 2014). "In our study we report frequent hypermethylation of ABCB4 in human cancers." (PMID 25367630, 2014). "Thus it will be interesting to further dissect the role of ABCB4 in the pathogenesis of cancer." (PMID 25367630, 2014).
cancer (continued). "As it was noted in the previous section, the overexpression of ATP-dependent efflux pumps, such as ABCB1, ABCB4 and ABCG2, is a common phenomenon in drug-resistant cancers and these genes were included in the “response to drug’’ process in our data." (PMID 36078127, 2022). "ABCB1, ABCB4, ABCG2, and ABCC2 are well-described markers of drug resistance development in many cancers." (PMID 31991882, 2020). "Sorcin gene is located in chromosome 7, in the same amplicon of other genes involved in the resistance to chemotherapeutic agents in cancer cells (multi-drug resistance, MDR), as the ABC transporters ABCB4 and ABCB1 (Mdr1, or P-glycoprotein 1)." (PMID 25197934, 2014). "Sorcin is highly expressed in the heart and in the brain, and is overexpressed in many cancer cells, being co-amplified with other proteins involved in the resistance to chemotherapy in cancer cells, as the ABC transporters ABCB4 and ABCB1." (PMID 25197934, 2014). "The epigenetic regulation ABCB4 in cancer has not been analyzed in detail." (PMID 25367630, 2014).
infection (11 papers, 2008 to 2025). The state of being infected such as from the introduction of a foreign agent such as serum, vaccine, antigenic substance or organism. "Competing DsRed virus, produced with wild type or mutant ABCB4, was added at a saturating multiplicity of infection (MOI) of 5 for mutant and at identical amounts of p24 for wild type." (PMID 18241333, 2008).
bacterial diseases (2 papers, 2009 to 2021). "To investigate how bacterial infection impacts placental efflux transport potential, we investigated the expression of the of Abca1, Abcb1a, Abcb1b, Abcb4, Abcc2, Abcc5, Abcf2, Abcg1 and Abcg2 mRNAs in the mouse placenta at GD15.5 or GD18.5 following LPS challenge (4 h)." (PMID 34394055, 2021). "The role of ABCB4 in bacterial diseases has not been reported so far." (PMID 19878563, 2009).
genetic disorder (2 papers, 2024 to 2025). "It is a genetic disorder caused by mutations in the ABCB4 gene (ATP-Binding Cassette Subfamily B Member 4), which encodes the MDR3 (MultiDrug Resistance 3) protein." (PMID 40499451, 2025).
metabolic disorders (2 papers, 2020). "Chronic cholangiopathy (Mdr2-/- Abcb4-/- mice); Lepob/ob mice with NASH; HFD induced metabolic disorders." (PMID 32982723, 2020).
cardiovascular diseases (1 paper, 2025). "Moreover, the p.N510S variant in ABCB4 was associated to an increased risk of cardiovascular diseases in the UKBB cohort, further underling the need of cardiovascular evaluation and personalised management of this patients." (PMID 39945383, 2025).
hepatobiliary disorder (1 paper, 2023). A non-neoplastic or neoplastic disorder that affects the liver, bile ducts, and gallbladder. "ABCB4 polymorphisms and deficiencies in humans are associated with a wide spectrum of hepatobiliary disorders, attesting to its crucial physiological function." (PMID 36901890, 2023).
liver (1 paper, 2020). "Hence, our data suggest that Abcb4−/− induced cholestatic liver injury might affect hepatic lipid metabolism by the activation of AMPK and CREB signaling in HBs transgenic mice." (PMID 32612285, 2020).
ABCB4 also shares sentences with these, for which no sentence is quoted: primary biliary cirrhosis (12 papers); Intrahepatic cholestasis of pregnancy (11); primary biliary cholangitis (9); liver dysfunction (5); Byler disease (4); Dubin-Johnson syndrome (4); benign recurrent intrahepatic cholestasis (3); cholera (3); chronic hepatitis (3); dyslipidemia (3); portal hypertension (3); bile duct carcinoma (2); cryptogenic cirrhosis (2); gastric cancer (2); gout (2); hepatitis (2); hepatitis B (2); inflammation (2); intestinal cancer (2); lung fibrosis (2); myotonic dystrophy (2); Nonalcoholic Steatohepatitis (2); pregnancy (2); prostate carcinoma (2); Pruritus (2); Pseudoxanthoma elasticum (2); Tangier disease (2); viral hepatitis (2); acute pancreatitis (1); adenocarcinoma (1).
A further 65 diseases each share a sentence with ABCB4 in 1 paper.